CHEK2 (checkpoint kinase 2)
Diseases named in the same sentence as CHEK2 in open-access papers (continued):
Sharing a sentence is not in itself a finding about the gene and the disease.
ovarian carcinoma (continued). "For example, the BARD1 and NBN (miR-548ai targets), BRIP1 (miR-567 target), and CHEK2 (miR-943 target) genes, which are known to be involved in breast and ovarian cancers." (PMID 34768979, 2021). "In Poland, founder mutations in BRCA1, BRCA2, PALB2, CHEK2, and RAD51C have been associated with familial breast and ovarian cancer." (PMID 33670479, 2021). "In some ovarian cancer cell lines, the cell cycle checkpoint and DDR functions of CHEK2 causes increased resistance to cisplatin." (PMID 34645978, 2021). "Remarkably, 2 of the 3 ATM mutation carriers of our cohort have first-degree relatives presenting with ovarian cancer, one of whom harbors the additional CHEK2 exon 9–10 deletion." (PMID 30086788, 2018). "In the present study we assessed the prevalence of CHEK2 germ line mutations in 145 BRCA1/2-negative early-onset and familial breast/ovarian cancer patients from Pakistan (Group 1)." (PMID 23806170, 2013). "In this first study of the prevalence of CHEK2 germ line mutations in 145 BRCA1/2-negative early-onset and familial breast and/or ovarian cancer from Pakistan two potentially deleterious mutations were identified." (PMID 23806170, 2013). "Screening for pathogenic variants in breast and ovarian cancer genes BRCA1/2, CHEK2 and RAD51C is common practice for individuals from high-risk families." (PMID 23239986, 2012). "Screening for pathogenic mutations in breast and ovarian cancer genes such as BRCA1/2, CHEK2 and RAD51C is common practice for individuals from high-risk families." (PMID 23239986, 2012). "In this study BRCA1, BRCA2 and CHEK2*(1100delC) were analyzed for mutations in 91 HBOC/HBC/HOC families and early onset breast and early onset ovarian cancer cases." (PMID 19656415, 2009). "Unlike BRCA1/2, PVs in ATM and CHEK2 do not confer sufficient ovarian cancer risk to warrant recommendation of risk-reducing salpingo-oophorectomy." (PMID 40298171, 2025). "Although the CHEK2 mutations were not confirmed as significant regarding the risk of ovarian cancer, other studies indicated that CHEK2 SNP rs17507066 had a significant association with the risk of HGSOC." (PMID 38275400, 2024). "Germline mutations of CHEK2 and BLM have been reported to be associated with several types of cancer, including prostate cancer, uterine serous carcinoma, and breast and ovarian cancer." (PMID 36053931, 2023). "Indeed, it has to be underlined that, beyond breast and ovarian cancers, pathogenic variants in BRCA1 and BRCA2, as well as in CHEK2 and PALB2, have been associated with a higher risk of developing an increasing number of cancers." (PMID 35456488, 2022). "Women who test positive for an inherited pathogenic/likely pathogenic gene variant in BRCA1, BRCA2, PALB2, CHEK2 and ATM are at an increased risk of developing certain types of cancer—specifically breast (all) and epithelial ovarian cancer (only BRCA1, BRCA2, PALB2)." (PMID 35681696, 2022). "However, patient adherence rates across all patients and their relatives indicate that identifying P/LP variants in ATM, CHEK2, PALB2, and other DDR genes associated with increased risk of breast and ovarian cancer also impact patient care." (PMID 35626031, 2022). "The detection of PALB2 and CHEK2 PGVs, in addition to PGVs detected in BRCA1/2, in breast/ovarian cancer is important for accurate risk assessment and the activation of subsequent cancer prevention and early detection strategies in the individual and their family." (PMID 34113003, 2021).
ovarian carcinoma (continued). "Particularly, the missense variant of CHEK2 I157T was significantly associated with ovarian cystadenomas, borderline ovarian tumors, and low-grade invasive cancers but not high-grade ovarian cancer." (PMID 26075229, 2015). "The other top hit was Colo704, an ovarian cancer cell line with homozygous deletion of CHEK2." (PMID 26437225, 2015). "The risk conferred by CHEK2 germ line mutations to breast and ovarian cancer in Asian populations is not well defined since most studies have determined the frequency of the c.1100delC mutation but did not evaluate other mutations." (PMID 23806170, 2013). "The significance of the CHEK2 1100delC mutation in individuals with a family history of ovarian cancer is not as well understood." (PMID 15535844, 2004). "While targeted treatments for ovarian cancer patients with CHEK2 mutations have not been prospectively confirmed, the presence of a DNA repair deficiency is in accordance with known hallmarks of cancer, and highlights possible utility of platinum or poly (ADP‐ribose) polymerase inhibitor (PARPi)." (PMID 38898688, 2024). "An analysis of the presence of mutations in BRCA1, BRCA2, RAD51C, PALB2, and CHEK2 with the age of onset of ovarian cancer revealed a lower age of ovarian cancer diagnosis in BRCA1 mutation carriers than in non-carriers of BRCA1 (51.6 vs. 57.6, p = 2.97 × 10−11)." (PMID 33670479, 2021). "Notably, 11.6% of patients proceeded with salpingo-oophorectomy, despite the fact that CHEK2 pathogenic variants are not known to be associated with increased risk for ovarian cancer." (PMID 33925588, 2021). "None of the four CHEK2 variants (CHEK2 c.349A>G (p.Arg117Gly); c.538C>T (p.Arg180Cys); c.715G>A (p.Glu239Lys) and c.1036C>T (p.Arg346Cys)) were found to be associated with an increased risk of prostate or ovarian cancer." (PMID 27595995, 2016). "Our findings suggest that CHEK2 missense mutations may not contribute significantly to breast/ovarian cancer susceptibility in Pakistan." (PMID 23806170, 2013). "Our findings suggest that CHEK2 mutations may not contribute significantly to breast/ovarian cancer risk in Pakistani women." (PMID 23806170, 2013). "BRCA2 and BRCA1 also reached this level for ovarian cancer, BRCA2, ATM, and CHEK2 for prostate cancer, and ATM for pancreatic cancer." (PMID 40073867, 2025). "This study demonstrates that, among patients with breast or ovarian cancer, positive genetic test results in ATM, CHEK2, PALB2, and other DDR genes impact clinical recommendations for the majority of patients and/or their family members." (PMID 35626031, 2022). "In this single-center comprehensive study of germline PALB2 PGVs and the CHEK2_1100delC PGV in breast/ovarian cancer, we show a 1% detection rate for PALB2 PGVs, 1.4% for CHEK2_1100delC, and ~7% for BRCA1/2 PGVs." (PMID 34113003, 2021). "Overall, 215 breast or ovarian cancer probands (64.8%) were tested, of which 41 resulted positive for BRCA and one for CHEK2 genes (19.5%)." (PMID 33710808, 2021). "Among CHEK2 missense (c.470T>C) mutation carriers, the family history of ovarian cancer was present in 3 (27.3%) patients with BOT and none with ovarian cancer G1." (PMID 35313928, 2022). "In our study, the association of CHEK2 missense mutation (c.470T>C) was statistically significant for BOT risk, but not for the risk of ovarian cancer G1." (PMID 35313928, 2022). "The real-world clinical impact of positive findings in ATM, CHEK2, PALB2, and other DDR genes conferring an increased risk of breast and/or ovarian cancer have not been well studied." (PMID 35626031, 2022). "The ovarian cancer risk was associated with mutations in BRCA1, BRCA2, RAD51C, and PALB2 but not in the CHEK2 gene." (PMID 33670479, 2021).
ovarian carcinoma (continued). "However, despite many published results, the association of CHEK2 mutations with ovarian cancer (or its particular non-high-grade subtypes) can be neither confirmed nor rejected, and it illustrates the stalemate situation with the clinical interpretation of germline CHEK2 variants." (PMID 33322746, 2020). "In this study, the effects of TF3 on apoptosis, as well as cell cycle distribution, were assessed and whether checkpoint kinase 2 (Chk2) and p27 kip1 (p27) were involved in TF3-mediated inhibition of human ovarian cancer cells was also investigated." (PMID 30769778, 2019). "We also observed pathogenic mutations in several genes that have not traditionally been associated with increased risk of ovarian cancer (PALB2, ATM, and CHEK2)." (PMID 28281021, 2017). "Therefore, the estimation of the contribution of CHEK2 and PALB2 pathogenic variants in hereditary breast and ovarian cancer risk is not possible based on the data presented herein, and is beyond the scope of this study." (PMID 35456488, 2022). "A study assessing CHEK2 and PALB2 mutations in high-risk Finnish BRCA1/2-founder mutation-negative breast and/or ovarian cancer individuals identified four cases of skin cancers with a co-occurring PALB2 and CHEK2 mutation, but unfortunately no details on the type of these cancers is included." (PMID 34084283, 2021). "In addition, literature data on the occurrence of BRCA1, BRCA2, CHEK2 and NBS1 mutations in non-selected ovarian cancer patients were reviewed." (PMID 19338682, 2009). "However, this study utilized a panel consisting of BRCA1/2, PALB2, CHEK2, and ATM only, whereas the GRACE panel was more extensive and included genes not traditionally associated with ovarian cancer, which explains our higher prevalence of P/LP variants overall." (PMID 39061202, 2024). "Nevertheless, the roles of checkpoint kinase 2 (Chk2) and p27 kip1 (p27) in TF3-mediated inhibition of human ovarian cancer cells have not yet been investigated." (PMID 30769778, 2019). "The results of our study suggest that CHEK2 (c.470T>C) may possibly play a role in the pathogenesis of BOT, but not low-grade ovarian cancer." (PMID 35313928, 2022).
prostate carcinoma (149 papers, 2003 to 2026). A carcinoma that arises from epithelial cells of the prostate gland. "CHEK2‐associated urological cancers included renal cancer (n=1) and prostate cancer (n=5), all of which showed favorable outcomes." (PMID 41970070, 2026). "In the Expert Consensus on HRR Gene Testing and Variant Interpretation in Prostate Cancer, CHEK2 has been explicitly classified as one of the HRR genes associated with the treatment efficacy of PARP inhibitors in prostate cancer." (PMID 41383501, 2025). "Pathogenic germline mutations in the CHEK2 gene are among the most frequent alterations in various tumors, and their role has been confirmed in gender-specific cancers such as breast and prostate cancer." (PMID 39595021, 2024). "In male carriers, the risk of prostate cancer is higher given that CHEK2 upregulation reduces cell growth whereas its downregulation alters androgen receptor activity." (PMID 38313678, 2024). "CHEK2 is a low-penetrance cancer susceptibility gene that increases risk for breast, colorectal, and prostate cancer." (PMID 39669616, 2024). "Prostate cancer cases carrying high-risk genetic variants in DNA repair pathway genes, such as CHEK2, have a greater risk of progression and are often early onset cases with a higher mutational burden." (PMID 38750076, 2024). "The second variant in CHEK2, c.592+3A>T, was identified in one family with both breast and prostate cancer cases and segregation analysis has confirmed the cosegregation of the variant with the disease." (PMID 38313678, 2024). "CHEK2 mutations were identified in three patients; mutations in this gene are associated with increased risk in breast, colon, and prostate cancer." (PMID 38700789, 2024). "For example, carriers of the CHEK2 allele previously reported to increased risk of prostate cancer had lower circulating concentrations of FLT3LG21,22." (PMID 38750076, 2024). "Additional genes on prostate cancer panels confer variable risks for prostate cancer, such as, for example, CHEK2 which has been reported to confer a modest increase in risk for prostate cancer." (PMID 37240284, 2023). "The estimated HR for prostate cancer associated with CHEK2 mutations was 8.6 (p = 0.29, 95% CI 0.40–182)." (PMID 35892882, 2022). "We provide evidence that novel germline mutations in ATM and CHEK2 are associated with aggressive prostate cancer." (PMID 35892882, 2022). "Two CHEK2 mutation carriers were identified who were diagnosed with prostate cancer at 80 and 56 years." (PMID 35892882, 2022). "Our cohort therefore contributes to evidence of prostate cancer predisposition for CHEK2 carriers and a relationship with aggressive disease, although larger numbers are required to solidify this association." (PMID 35892882, 2022). "Germline pathogenic and likely pathogenic (P/LP) variants in CHEK2 have been associated with increased prostate cancer (PrCa) risk." (PMID 36360192, 2022). "The possible association between CHEK2 germline pathogenic variants and risk of prostate cancer still requires clarification due to the few and conflicting reports to date." (PMID 33804961, 2021). "Truncating CHEK2 variants have also been shown to confer a slightly increased risk for gastric cancer, kidney cancer, sarcoma, prostate cancer, and colorectal cancer, with the relative risk for the latter estimated to be 1.88." (PMID 34711244, 2021). "In familial cases, CHEK2 mutations are associated with an increased risk of prostate cancer (OR 3.39; 95% CI, 1.78–6.47)." (PMID 32197306, 2020). "The association of CHEK2 with prostate cancer was already proposed in 2003, when Dong and colleagues identified 18 unique CHEK2 mutations in 15/400 (3.75%) patients with sporadic prostate cancer and in 11/298 (3.69%) patients with familial prostate cancer." (PMID 33322746, 2020). "Wu and colleagues analyzed survival characteristics in prostate cancer patients carrying germline CHEK2 mutations." (PMID 33322746, 2020).
prostate carcinoma (continued). "The performed studies present rather compelling evidence that CHEK2 is a low-to-moderate prostate cancer predisposition gene." (PMID 33322746, 2020). "As shown from the figure, PARP1 (cluster 1) was found to have conditional essentiality with cell lines having mutation in CHEK2 (cluster 3) and a survival advantage of down regulation of PARP1 in prostate cancer patients when CHEK2 was mutated." (PMID 31709193, 2019). "CHEK2 variants predispose individuals to breast and colon cancer and it has been shown to be a negative regulator of prostate cancer growth." (PMID 30305041, 2018). "The CHEK2 c.1100delC mutation has been also linked to an increased risk for prostate cancer, and possibly indicates an elevated risk for metastatic prostate cancer." (PMID 28874143, 2017). "Extending the use of PARP inhibitors, beyond tumors with defective BRCA1/2, ATM, CHEK2, Fanconi's Anemia genes is of great interest, expecially in prostate cancer, where mutations in DNA repair genes are rare." (PMID 28415632, 2017). "LOX-PP also inhibits radiation-induced activating phosphorylation of ataxia-telangiectasia mutated (ATM) and checkpoint kinase 2 (CHK2) to inhibit DNA repair pathways in prostate cancer xenograft growth." (PMID 28036074, 2016). "Evidence for prostate cancer risk was observed for CHEK2 c.1343T>G OR 3.03 (95% CI 1.53 to 6.03, p=0.0006) for African men and CHEK2 c.1312G>T OR 2.21 (95% CI 1.06 to 4.63, p=0.030) for European men." (PMID 27595995, 2016). "In conclusion, potential germline mutations affecting the CHEK2 gene should be taken into consideration when exploring the genetic mechanisms of drug resistance among breast and, most likely, also prostatic cancer patients." (PMID 27708748, 2016). "Because odds ratios were reported for prostate cancer with this mutation range between 2.0 and 3.0, it is reasonable to suggest screening for CHEK2 mutations in men." (PMID 25431674, 2014). "CHEK2 is a multi-cancer susceptibility gene whose common germline mutations are known to contribute to the risk of developing breast and prostate cancer." (PMID 24986639, 2014). "Men with CHEK2 mutations and family history of prostate cancer show a higher risk of prostate cancer." (PMID 25431674, 2014). "In this review, we provide an overview of the current knowledge of the role of a genetic variant, 1100delC, of CHEK2 on prostate cancer risk and discuss the implication for potential translation of this knowledge into clinical practice." (PMID 25431674, 2014). "Among numerous mutations identified in CHEK2, the best studied mutations in prostate cancer are 1100delC, IVS2+1G>A, I157T, and del5395." (PMID 25431674, 2014). "Thirty-three different mutations were identified in CHEK2 from 876 DNA samples from various prostate cancer patients." (PMID 25431674, 2014). "The excess risk of prostate cancer attributable to a CHEK2 mutation was restricted to carriers of the VV genotype at p27." (PMID 19401704, 2009). "Several studies have reported associations of germline mutations in CHEK2, especially the 1100delC mutation, with increased susceptibility to breast and prostate cancer." (PMID 15535844, 2004). "While this manuscript was in preparation, another study was published showing that mutations in CHEK2 were associated also with prostate cancer risk." (PMID 14612911, 2003). "Our results suggest that CHEK2 1100delC mutation is associated with positive family history of prostate cancer." (PMID 14612911, 2003). "The present results warrant further studies of the role of CHEK2 variants as a risk factor for prostate cancer in other populations." (PMID 14612911, 2003). "The results suggest that CHEK2 variants are low-penetrance prostate cancer predisposition alleles that contribute significantly to familial clustering of prostate cancer at the population level." (PMID 14612911, 2003). "Germline CHEK2 mutations have also been implicated in predisposition to breast and prostate cancer." (PMID 41294693, 2025).